MGAT5 (alpha-1,6-mannosylglycoprotein 6-beta-N-acetylglucosaminyltransferase)
Diseases named in the same sentence as MGAT5 in open-access papers (continued):
Sharing a sentence is not in itself a finding about the gene and the disease.
cancer (72 papers, 2007 to 2025). A tumor composed of atypical neoplastic, often pleomorphic cells that invade other tissues. "mRNA expression of MGAT5 is upregulated by the oncogenic Ras-Raf-Ets pathway in various cancer cells, and higher expression of GnT-V is associated with poor prognosis of cancer patients." (PMID 38879010, 2024). "The number of MGAT5 glycan products typically increases in malignant tumors and is associated with disease progression." (PMID 37256183, 2023). "The products of N-acetylglucosaminyltransferase V (GnT-V encoded by the Mgat5 gene), β1,6GlcNAc-branched N-glycans, have been associated with cancer growth, invasion, metastasis, and drug resistance." (PMID 36813234, 2023). "Regarding N-glycans, the β1,6-GlcNAc–branched N-glycans are widely overexpressed in cancer cells, being associated with increased expression of N-acetylglucosaminyltransferase V (GnT-V), responsible for its biosynthesis, which is encoded by the MGAT5 gene." (PMID 36827215, 2023). "MGAT5 adds the GlcNAcβ-1-6 branch to complex N-glycans and is associated with cancers and tumor progression." (PMID 36499281, 2022). "Surprisingly, enzymes responsible for the biosynthesis of well-known cancer-associated structures, such as β1,6 branching (MGAT5), sialyl-Tn (ST6GALNAC1) sLex (FUT6), Sia6LacNAc (ST6GAL1), and core-fucosylation (FUT8) lack any relationship with survival." (PMID 33919332, 2021). "This altered glycosylation is a result of the increased activity of N-acetylglucosaminyltransferase V (GnT-V), encoded by the mannoside acetylglucosaminyltransferase 5 (MGAT5) gene, which is upregulated in cancer." (PMID 33671245, 2021). "A possible mechanism by which MGAT5 upregulation enhances cancer progression is by causing a high frequency of branched N-glycans on the extracellular domains of Receptor Tyrosine Kinases (RTKs)." (PMID 32340396, 2020). "In parallel, the increase of β1-6 highly branched N-glycans observed in cancer cells is also due to upregulation of N-acetylglucosaminyltransferase V enzyme (GnT-V encoded by MGAT5 gene)." (PMID 32872358, 2020). "Growth factor receptors are examples of MGAT5 substrates, and MGAT5 overexpression is associated with growth, adhesion, invasion and metastasis of cancer." (PMID 32849657, 2020). "β1,6-N-acetylglucosaminyltransferase V (GnT-V; MGAT5) is one of the most relevant glycosyltransferases associated with cancer migration, invasion, and metastasis." (PMID 27686492, 2016). "GnT-V, a glycosyltransferase encoded by the Mgat5 gene that catalyzes the formation of β1,6GlcNAc (N-acetylglucosamine) branches on N-glycans, is believed to be associated with cancer growth and metastasis." (PMID 24349959, 2013). "MGAT5, a typical cancer-associated glycosyltransferase, is located in 2q21.2-q21.3." (PMID 33879098, 2021). "Conversely, Mgat5-deficient mice show reduced cancer growth in a mammary tumor mouse model." (PMID 31936666, 2020). "We questioned whether the cancer-associated glycosyltransferase MGAT5 is required for MICA expression." (PMID 32849657, 2020). "In addition, cancer-associated aberrant glycosylation increases the transcription of MGAT5, which initiates β1,6GlcNAc branching in tri- and tetra-branched N-glycans in PC, that was reported to play an important role in the metastasis." (PMID 31727974, 2019). "MGAT5 gene encodes an enzyme named N-acetylglucosaminyltransferase V that catalyzes the formation of β1, 6-branched N-glycans, which strongly associates with cancer metastasis." (PMID 29069753, 2017). "Most of the cancer-associated changes of oligosaccharide structure of glycoproteins are because of the abnormal expression of glycosyltransferase genes, such as N-acetylglucosaminyltransferase V (GnT-V, also known as Mgat5) 2–4." (PMID 24913443, 2014). "In contrast, N-acetylglucosaminyltransferase V (GnT-V) could add the GlcNAc β1-6 branches to N-glycan at the Man α1-6 side of the trimannosyl core and encoded by Mgat5 gene, it was strongly associated with cancer metastasis." (PMID 23977005, 2013).
cancer (continued). "Depleting MGAT5 or inhibiting N-glycosylation effectively suppresses ALK4-loss-induced TGF-β signaling and cancer progression." (PMID 41408046, 2025). "The activity of GlcNAc transferaseV (MGAT5) primes the biosynthesis of an N-glycan antenna that is heavilyupregulated in cancer." (PMID 39287665, 2024). "Analysis of The Cancer Genome Atlas Program (TCGA) and Genotype-Tissue Expression (GTex) project revealed significantly increased Mgat5 expression in human PDAC samples as compared with normal pancreas samples." (PMID 38912584, 2024). "Dysregulated formation of the branch produced by N-acetylglucosaminyltransferase-V (GnT-V, also called as MGAT5) promotes cancer growth and malignancy." (PMID 35915223, 2022). "Considering transcriptional regulation, an oncogenic signaling cascade—the Ras–Raf–Ets pathway—drives the MGAT5 gene, which suggests involvement of GnT-V in cancer." (PMID 35915223, 2022). "Knockdown of MGAT5 in cancer cells has been shown to reduce N-glycan branched on N-CAD and turnover of cell-cell adhesions, as well as cell migration." (PMID 33894774, 2021). "We also measured the protein levels of three glycosyltransferases (MGAT3, MGAT4a, and MGAT5) previously reported to correlate with CD147 glycosylation in clinical samples such as cancer tissues." (PMID 35050217, 2021). "The raised level of GlcNAc-branching N-glycans is a result of increased activity of mannoside N-acetylglucosaminyltransferase 5 (GnT-V), which is encoded by the MGAT5 gene, often activated in cancer cells." (PMID 34359624, 2021). "MGAT5 catalysing multibranched N-glycans is a critical regulators of stiffness induced invasion and GSCs mechanotransduction, underpinning MGAT5 as a serious target to treat cancer." (PMID 33894774, 2021). "We propose that the mechanisms involving MGAT5 in EMT processes is mediated by fine sensing of the stiffness leading to ZEB1 expression modulation, and regulate key oncogenic functions, making MGAT5 as a serious target to treat cancer." (PMID 33894774, 2021). "It is derived from an upregulation of the N-acetylglucosaminyltransferase V (MGAT5) by oncogenic transcription factors from the RAS–RAF–MAPK signaling pathways, which are highly associated with cancer metastasis." (PMID 32340396, 2020). "Based on this relationship, the present results, showing a higher cancer/normal ratio of MGAT3 expression compared with that of MGAT5 expression, are supportive evidence for the increase in bisecting GlcNAc in PDAC tissues." (PMID 32232009, 2020). "Expression of the MGAT5 gene in various human cancer types is aberrantly driven by the oncogenic Ras-Raf-ETS pathway." (PMID 31936666, 2020). "We found that basal MICA expression in MGAT5 KO cells as well as several cancer cells, is downregulated in response to ACLY inhibition with HC." (PMID 32849657, 2020). "The increased uptake of glucose and conversion to intracellular lactate in MGAT5 KO cells resembled elevated aerobic glycolysis, which is one of the hallmarks of cancer and supports increased growth and proliferation." (PMID 32849657, 2020). "In line with this, our data suggest that MGAT5 KO increases NKG2DLs, which would support cancer elimination in response to MGAT5 inhibition." (PMID 32849657, 2020). "Consistent with this, mRNA levels of MGAT5 gene are upregulated in various cancer types by direct transcriptional activation of the oncogenic Ras-Raf-Ets pathway." (PMID 30140003, 2018). "The Warburg effect was first described in cancer cells, where branching and Mgat5 are pathologically over-expressed and serve as essential drivers of growth, motility and metastasis." (PMID 28059703, 2017). "MGAT5 is considered to be an upstream regulator that affects many target proteins to promote cancer metastasis including MT1-MMP and TIMP-1." (PMID 28178684, 2017).
cancer (continued). "Collectively, these results indicate that MGAT5 confers survival advantages to cancer cells in an anchorage-dependent and -independent manner that would otherwise undergo apoptotic death following anoikis stress." (PMID 28178684, 2017). "Our data in T cells suggest that although increased GFPT and MGAT5 expression in cancer drive UDP-GlcNAc and branching, aerobic glycolysis is expected to do the opposite and limit UDP-GlcNAc expression and branching." (PMID 28059703, 2017). "As example, RAS-RAF-MAPK signaling pathway is frequently upregulated in cancer cells and is particularly involved in the increased expression of the MGAT5 gene that encodes human N-acetylglucosaminyltransferase V (also known as GnT-V)." (PMID 28880250, 2017). "In these regards, identifying the target proteins of MGAT5 and understanding the molecular mechanisms behind the interplay between MGAT5 and its target proteins are necessary to establish the best strategy to control anoikis resistance in cancer cells." (PMID 28178684, 2017). "Taken together, the interference RNA-based approach enabled us to confirm that the viability of anokis-exposed cancer cells is critically enhanced by the MGAT5 expression level." (PMID 28178684, 2017). "The MGAT5-stimulated anoikis resistance was validated in clinical specimens by correlating the MGAT5 mRNA levels to the cancer stage." (PMID 28178684, 2017). "Many reports have revealed that the levels of MGAT5 mRNA and its enzymatic product β1,6-branch are aberrantly upregulated in cancer cells and that this β1,6-branch is highly involved in cancer growth and metastasis." (PMID 27136596, 2016). "The expression levels of N-glycans with a β1,6-branched structure, as well as the expression level of MGAT5, were maximized by the introduction of hTERT, which is reasonable considering that MGAT5 is involved in cancer development." (PMID 26132161, 2015). "Our results further showed that tumors derived from Mgat5 KO mice presented a tendency for lower levels of the immune checkpoint inhibitor PD-L1 molecules in the carcinoma stage, which is in line with the activating and non-immunosuppressed phenotype of T cells in KO mice." (PMID 40087977, 2025). "Mgat5 glycans allow cancer cells to evade T cell–mediated clearance." (PMID 38912584, 2024). "Mgat1 and Mgat5 were found to serve important roles in a number of cellular functions, including cell death and survival, protein synthesis, cellular movement, post-translational modification, protein degradation, and cancer." (PMID 36499281, 2022). "In conclusion, measurement of the ECM stiffness and MGAT5-dependent N-glycan branching may be a better indicator of cancer cell invasiveness than either alone." (PMID 33894774, 2021). "These are all traits of cancer metabolism and could infer that MGAT5 KO cells resemble cancer cells metabolically." (PMID 32849657, 2020). "To study whether MGAT5 and MMP9 are required for Barx1-mediated cancer cell invasion and metastasis, we reduced the expression of MGAT5 and MMP9 in SMMC7721-shBarx1 cells with shRNA knockdown." (PMID 29069753, 2017). "However, the effect of MGAT5 expression on cancer cell proliferation was much more dramatic for anoikis cells under both anchorage-dependent and -independent conditions." (PMID 28178684, 2017). "We tested whether the MGAT5-stimulated anoikis resistance culminates in enhanced cancer cell growth under varying conditions." (PMID 28178684, 2017). "Next, we checked whether the anoikis resistance gained by MGAT5 overexpression favors cancer cell proliferation under anchorage-dependent as well as -independent conditions." (PMID 28178684, 2017). "Further, and owing to increased MGAT5 expression and GnT-V activity frequently observed in a cancer cell, E-cadherin is predominantly targeted by GnT-V-mediated glycosylation at the Golgi apparatus, where β1,6-GlcNAc-branched N-glycans are added to Asn-554 of E-cadherin." (PMID 27533452, 2016).
cancer (continued). "Furthermore, MGAT5 transcripts and/or their products, β1,6-branch, are often upregulated in many types of cancer, such as gastric, esophageal, colon and liver cancers." (PMID 27136596, 2016). "Notably, MGAT5 depletion in cancer models reduces metastasis and cell proliferation." (PMID 41408046, 2025). "Finally, the inability to produce Mgat5 glycans potentiates the activity of ICB, suggesting that targeting Mgat5 may improve the efficacy of cancer immunotherapy." (PMID 38912584, 2024). "The changes in specific N-glycan structures according to the type of cancer observed here can be explained by the opposing roles of MGAT3 and MGAT5." (PMID 36890858, 2023). "MGAT5 inhibition by the drug PST3.1a reduced invasiveness, proliferation and EMT of glioma cancer stem cells." (PMID 34356834, 2021). "We find that glycolysis and mitochondrial export of citrate promotes constitutive MICA transcription in MGAT5 KO cells, a regulation that was also shown in several MICA-expressing cancer cells." (PMID 32849657, 2020). "Ongoing investigations are exploring how MGAT5 and galectin-3 modulate other key receptors, including VEGFR and integrins, in cancer models, which could provide additional therapeutic strategies." (PMID 41408046, 2025). "We observed a significant overexpression of Mgat5 glycogene as well as Mgat4a and Mgat3 in LGD, HGD, and carcinoma, when compared with inflamed tissue, suggesting an overall increase in complex N-glycosylation pathway along CAC development, which is in accordance with our human results." (PMID 40087977, 2025). "Moreover, Mgat5 KO mice tumors also showed increased levels of MHC-I in both dysplasia and carcinoma compared with WT mice, further supporting increased antigen presentation and antitumor immune activation." (PMID 40087977, 2025). "In ovarian and triple negative breast cancer cells, treatment with the DNA methyltransferase inhibitor 5-AZA-2-deoxycytidine activated MGAT5 transcription, resulting in increased migration and EMT, highlighting the potential side effects of epigenetic therapeutics in cancer treatment." (PMID 34356834, 2021). "MGAT5 expression levels, which have been shown to be driven by the oncogenic RAS-RAF-ETS1 pathway, are elevated in various cancer types." (PMID 33963380, 2021). "Increasing in β1,6 GlcNAc branching and MGAT5 expression in the highly metastatic SKOV3-ip cells were also manifested, which were in accordance with findings reported in other cancers." (PMID 24516574, 2014). "One mechanism reported to be responsible for inhibitory effects of MGAT3 on cancer metastasis is that addition of bisecting GlcNAc by MGAT3 hinders β1,6 GlcNAc branching formation catalyzed by MGAT5, since MGAT5 cannot utilize the bisected oligosaccharide as an acceptor substrate." (PMID 24516574, 2014). "In accordance, the absence of β1,6-GlcNAc branched N-glycans in Mgat5 KO mice was balanced by an increase in mannosylated N-glycans (less complex type of glycans) on T cells in advanced stages of the disease (dysplasia and carcinoma)." (PMID 40087977, 2025). "Since the methylation status of MGAT5 did not change along EMT, it might be upregulated by the E26 transformation-specific (ETS) transcription factor family through the HER2 pathway, resulting in highly branched N-glycan structures on cancer cells." (PMID 27446804, 2016).
infection (1 paper, 2023). The state of being infected such as from the introduction of a foreign agent such as serum, vaccine, antigenic substance or organism. "A study examining Gal-3 and N-acetylglucosaminyltransferase V (Mgat5) in MVM infection found that both are crucial for efficient cell entry and infection, with cancer cells expressing higher levels of Gal-3 being more susceptible to MVM infection." (PMID 37298569, 2023).
neurodegenerative disease (1 paper, 2021). A disorder of the central nervous system characterized by gradual and progressive loss of neural tissue and neurologic function. "N-glycan branching on lymphocytes and oligodendroglial progenitors mediated by β1,6-N-acetylglucosaminyltransferase V (Mgat5/GnTV) influences galectin-binding, modulating inflammatory responses and remyelination in neurodegenerative diseases." (PMID 34720894, 2021).
neurological disease (1 paper, 2022). "Notably, the Mgat5−/−:Npc1−/− mice were smaller than the single mutant Npc1−/− mice but appeared to be mobile and exhibited normal behavior prior to the onset of the neurological disease." (PMID 35563467, 2022).
MGAT5 also shares sentences with these, for which no sentence is quoted: bladder cancer (7 papers); non-small cell lung carcinoma (6); fibrosarcoma (4); lung adenocarcinoma (3); endometrial cancer (2); immune system disease (2); lymph node metastasis (2); rheumatoid arthritis (2); squamous cell carcinoma (2); thyroid cancer (2); alcohol dependence (1); anaplastic carcinomas (1); cardiac hypertrophy (1); Cognitive impairment (1); congenital disorder of glycosylation (1); Crohn disease (1); diabetes (1); diabetic cardiomyopathy (1); diabetic retinopathy (1); dysplasia (1); esophageal cancer (1); follicular adenomas (1); follicular carcinomas (1); heart failure (1); Hyperglycemia (1); hypertrophy (1); inflammation (1); Lewis lung carcinoma (1); liver cirrhosis (1); lung carcinoids (1).
A further 15 diseases each share a sentence with MGAT5 in 1 paper.